MGMT (O-6-methylguanine-DNA methyltransferase)
Diseases named in the same sentence as MGMT in open-access papers (continued):
Sharing a sentence is not in itself a finding about the gene and the disease.
glioma (continued). "The association between LGALS3 and glioma clinically relevant diagnostic/molecular markers (IDH, 1p19q, ATRX, MGMT, and TERT) was examined using the Chi-Squared (χ2) test." (PMID 32528967, 2020). "All 9 hypermutated gliomas had MGMT promoter methylation and were post-TMZ, and 5/9 (56%) were IDH1 mutant." (PMID 32051040, 2020). "MGMT gene promoter methylation was observed in 60.3% (n = 38) of the glioma samples versus 39.7% (n = 22) unmethylated cases." (PMID 33552543, 2020). "First, we found that FTL expression was positively correlated with MGMT expression in glioma tissues in three public datasets (TCGA,CGGA and Rembrandt)." (PMID 32677981, 2020). "A few studies have shown that deep learning can be used to segment tumors and predict MGMT methylation status for glioma." (PMID 33029531, 2020). "Based on this cohort, we outline the extent of MGMT promotor methylation and its potential prognostic value in patients with glioma WHO grade II." (PMID 33184319, 2020). "Coexistence of MGMT methylation and IDH mutation was seen in 47.1% glioma grade II, 33.3% glioma grade III, and 14.8% glioma grade IV." (PMID 33247700, 2020). "The role of the MGMT methylation status on benefit from temozolomide in IDH mutant (IDHmt) lower-grade gliomas is less clear, although most cases (>80%) show methylation at the MGMT promoter." (PMID 31968687, 2020). "Wu and coworkers studied TMZ and molecular mediators for its clinical response in glioma patients with tumors that have a methylated O6-methylguanine DNA methyltransferase (MGMT) promoter." (PMID 32610540, 2020). "Kong and colleagues used FDG PET-based radiomics in 107 patients with primary glioma and extracted a total of 1561 features for prediction of MGMT promoter methylation status." (PMID 32394100, 2020). "Several clinically significant molecular alterations (including mutations in IDH, 1p/19q, MGMT, and EGFR) have been described in gliomas and combined with histology for tumor classification." (PMID 33614625, 2020). "First, the fact that MGMT methylation coexist with IDH mutation, which is commonly seen in low grade gliomas, made their occurrence much more frequent than high grade gliomas with less IDH mutation." (PMID 33247700, 2020). "A combination of MGMT promoter methylation and IDH mutation is now believed to significantly increase the overall survival (OS), and progression-free possibilities in glioma patients." (PMID 33552543, 2020). "ML has been used on gliomas to predict OS using various datasets, especially TCGA, studying IDH mutation and MGMT promoter methylation." (PMID 33552543, 2020). "Novel biomarkers such as isocitrate dehydrogenase 1 gene (IDH1) and O6-methylguanine-DNA-methyltransferase (MGMT) gene methylation status have been proposed as useful tool to predict prognosis and survival of glioma patients." (PMID 33282092, 2020). "Implications of MGMT promotor methylation on outcome in glioma WHO grade II warrants evaluation in prospective clinical cohorts undergoing standardized therapeutic approaches." (PMID 33184319, 2020). "The methylation status of MGMT promoter is an important factor in the clinical treatment of glioma patients." (PMID 31907037, 2020). "High BACE2 expression was related to wild‐type IDH1 in glioma patients, while low BACE2 expression was associated with other features, including MGMT promoter methylation, 1p/19q codeletion, TERT loss and ATRX mutation." (PMID 31856384, 2020). "The O6-alkylguanine DNA alkyltransferase gene (MGMT), a DNA repair gene, is the most prominent epigenetic biomarker in gliomas and its alterations play a central role in GMB classification, treatment, and survival outcomes." (PMID 31968687, 2020). "The median overall survival for grade III glioma patients with MGMT promoter-methylation was 171.0 (95% CI: 115.4–226.6) months compared to just 44.3 (95% CI: 39.3–49.3) months in those without the mutation (p = 0.006)." (PMID 32005184, 2020).
glioma (continued). "IDH1 mutants were observed in 23 (60.5%) of the 38 MGMT promoter-methylated glioma cases compared with wild-type 15 (39.5%), while six (27.3%) IDH1 mutants were found in 22 unmethylated cases versus 16 (72.7%) wild-type cases." (PMID 33552543, 2020). "In this study, we investigated the therapeutic effects of MDRmiRs for the enhancement of chemotherapeutics using a glioma cell line (T98G) with high MGMT expression and a triple-negative breast cancer cell line (MDA-MB-231-luc) with high ABCB1 expression." (PMID 32029822, 2020). "miR-181d, which is downregulated in gliomas, targets O6-methylguanine DNA methyltransferase (MGMT), a protein that is critical for maintaining genomic stability." (PMID 33291485, 2020). "Subgroup analysis by ethnicity in the grade III glioma group showed that Malays had the highest incidence of positive results for two biomarkers: 60% for MGMT promoter methylation and 67% for 1p19q co-deletion." (PMID 32005184, 2020). "A number of important molecular biomarkers that are prognostic and/or predictive have already been identified in glioma patients including 1p19q co-deletion, IDH1 mutation, and MGMT methylation." (PMID 32355162, 2020). "We note that though the MGMT phenotypic selection is reversible, MGMT returns to the initial amount on a timescale which is consistent with the cell doubling time (which can be long for glioma cells)." (PMID 32874597, 2020). "We also explored the impact of these biomarkers on overall survival in our population and found that longer overall survival was associated with the presence of MGMT promoter methylation (in grade III and IV) and 1p19q co-deletion (in grade III glioma only)." (PMID 32005184, 2020). "Gliomas with evident MGMT methylation had a higher mean APTw = 2.38±.81% (n = 10, subjects 1, 5, 6, 10, 13, 17, 19, 20, 21 and 22) compared to those without MGMT methylation; mean APTw = 1.92±.33% (n = 3 subjects)." (PMID 33373375, 2020). "By leveraging the CRISPR/Cas9 technology we generated some of these MGMT rearrangements in glioma cells and demonstrated that the MGMT genomic rearrangements contribute to TMZ resistance both in vitro and in vivo." (PMID 32753598, 2020). "The discovery that differential MGMT promoter methylation in GBM plays a key role in the understanding of glioma biology." (PMID 33041828, 2020). "A large number of reports have confirmed that MGMT methylation has impact on the therapeutic effect of the temozolomide chemotherapy and radiotherapy for high-grade gliomas." (PMID 32513276, 2020). "Experimental results demonstrate promising performance on accurate glioma delineation (Dice score, 0.897) and MGMT status prediction (accuracy, 0.827; recall, 0.852; precision, 0.821; and F1 score, 0.836) coming from the model trained with FLAIR images." (PMID 33029531, 2020). "Acknowledging minimal heterogeneity, we believe that our meta-analysis provides robust and useful directionality regarding the potential interaction between TERT and MGMT in glioma patients." (PMID 32957941, 2020). "FTL expression segregated glioma patients who were treated with TMZ or with high MGMT promoter methylation into survival groups in TCGA dataset." (PMID 32677981, 2020). "For glioma segmentation, one state-of-the-art deep model is utilized and obtains impressive performance on the involved MGMT dataset for GBM segmentation." (PMID 33029531, 2020). "It has been established that there is a significant correlation between NF-κB expression and MGMT expression in gliomas from different origins, as confirmed with immunohistochemistry assessments." (PMID 35582224, 2020). "Their expression levels were also related to the clinicopathological features of glioma, such as IDH mutation status, 1p/19q co-deletion status, MGMT methylation status and WHO grade." (PMID 32793593, 2020).
glioma (continued). "On the contrary, patients in the low-risk group had primary gliomas, LGG histology, low-grade, young group, IDH mutant type, 1p/19q codeletion (P < 0.001), and MGMT promoter methylation (P = 0.004)." (PMID 33330074, 2020). "Multivariate analysis of glioma patients according to different clinical parameters and MGMT promoter methylation." (PMID 33552543, 2020). "In glioma cells, resveratrol increased sensitivity to temozolomide-induced apoptosis by downregulating the activity and expression of the DNA repair protein, MGMT." (PMID 32878338, 2020). "The detection of several molecular markers, including IDH1 mutation, 1p/19q codeletion, MGMT promoter methylation status, and EGFR amplification has been applied with clinical diagnoses of gliomas." (PMID 33692940, 2020). "Screening for hypermutation-associated MMR defects therefore appears to be of greatest value in recurrent, post-TMZ gliomas, especially MGMT-methylated and/or IDH1 mutant tumors." (PMID 32051040, 2020). "Factors including age at diagnosis, WHO grade, IDH status, MGMT promoter status, EGFR status and risk score were statistically related with the overall survival (OS) of glioma patients." (PMID 32373523, 2020). "MGMT expression was first proposed to be a resistance factor in glioma in the 1990s, following mechanistic findings from the laboratory identifying a role for MGMT in DNA repair following alkylating agent-mediated injury." (PMID 32083011, 2020). "In glioma, patient sensitivity to TMZ and the associated enhanced overall survival are frequently linked to low MGMT expression and increased MGMT promoter methylation." (PMID 32372061, 2020). "MGMT is a DNA repair enzyme that protects normal and glioma cells from alkylating chemotherapeutic agents." (PMID 32705083, 2020). "The strengths of this study lie in the fully automatic glioma segmentation and predicting the MGMT methylation status based on a small dataset." (PMID 33029531, 2020). "Methylation of the MGMT promoter is a favorable predictive factor in the treatment of glioma patients with temozolomide." (PMID 32295203, 2020). "In 2016, WHO conducted a molecular classification for glioma, pointing out the heterogeneity of glioma in various molecular states including IDH mutation status and MGMT promoter methylation status." (PMID 32851059, 2020). "In the 23 gliomas with MGMT promoter methylation information, the MGMT promoter of all 18 H3 K27M-mutant gliomas were unmethylated, and 3/5 H3-wildtype gliomas had methylated MGMT promoters." (PMID 32228694, 2020). "This metabolite acts by hypermethylation at GGG DNA sequences and inactivation of repair enzyme O6 methylguanine-DNA methyltransferase (MGMT) which initiates apoptosis, ultimately resulting in glioma cell death." (PMID 32995109, 2020). "In the clinical treatment of glioma, the MGMT promoter methylation status is an important prognostic indicator, because patients with MGMT promoter methylation are prone to benefit from TMZ treatment." (PMID 31907037, 2020). "We then analyzed 36 O-6-methylguanine-DNA methyltransferase (MGMT) unmethylated lower-grade gliomas from patients seen at West China Hospital of Sichuan University." (PMID 33392065, 2020). "A second, equally important molecular property in gliomas bearing great prognostic relevance is the MGMT promotor methylation status." (PMID 32158691, 2020). "The median overall survival for grade IV glioma patients with MGMT promoter-methylation was 57.1 (95% CI: 52.8–45.6) months compared to 50.2 (95% CI: 44.1–56.2) months in those without the mutation (p = 0.051)." (PMID 32005184, 2020). "MGMT methylation status is determined for all GBMs in 37% of laboratories, whereas 35% analyze tissue from all gliomas (also lower grades) at the time of primary surgery." (PMID 32025325, 2020). "We introduce molecular (MGMT methylation, IDH mutation, 1p/19q co-deletion, ATRX mutation, and TERT mutations) prediction methods of low-grade gliomas with imaging." (PMID 32111869, 2020).
glioma (continued). "Another study showed that VPA down-regulates the expression of MGMT and sensitises glioma cells to TMZ33." (PMID 32612203, 2020). "The overall survival of secondary gliomas in the MGMT-unmethylated cohort were influenced independently by the use of temozolomide during the treatment of formerly low-grade gliomas (p=0.00096)." (PMID 33392065, 2020). "In our study, the incidence of MGMT promoter methylation in high-grade gliomas was 55% in grade III gliomas and 30% in grade IV gliomas." (PMID 32005184, 2020). "Here we show that a subset of recurrent gliomas carries MGMT genomic rearrangements that lead to MGMT overexpression, independently from changes in its promoter methylation." (PMID 32753598, 2020). "Meanwhile, the molecular basis and prognosis of glioma patients with different IDH mutation status and MGMT promoter methylation status are significantly different." (PMID 32851059, 2020). "Glioma O6-methylguanine-DNA methyltransferase (MGMT) promoter methylation status informs clinical decision making." (PMID 32025325, 2020). "Radiomics has proven the potential for the genotype classification of prognostic factors to predict IDH status, 1/19q codeletion status, or MGMT methylation status in glioma-related studies." (PMID 33746649, 2020). "By analyzing the RNA-seq data of 252 recurrent gliomas, we identified eight different MGMT fusions in seven patients (~3% of all patients, 95% CI, 1.1–5.6%)." (PMID 32753598, 2020). "MGMT promoter methylation was associated with a superior OS in both TERT-mut (HR = 0.29; 95% CI = 0.21–0.39; I2 = 44%) and TERT-wt gliomas (HR = 0.54; 95% CI = 0.39–0.74; I2 = 19%)." (PMID 32957941, 2020). "It has been shown that MGMT promoter methylation is a good prognostic factor for patients with glioma treated with temozolomide, another alkylating drug." (PMID 32870234, 2020). "MGMT promotor methylation is considered an important biomarker for outcome in glioma WHO grade III and IV." (PMID 33184319, 2020). "This process is believed to render MGMT methylation a favorable prognostic advantage in glioma patients treated with alkylating agents." (PMID 33552543, 2020). "We treated three other glioma cell lines having different MGMT status (U87, LN18, and A172 cells) with TMZ at various concentrations (250, 350, and 50 μM, respectively) and analyzed the expression of the four genes." (PMID 31907355, 2020). "We found that the risk scores of the signature of the 19 ferroptosis-related genes was negatively correlated to the expression of the well-recognized gene MGMT for TMZ resistance, suggesting the association of ferroptosis with glioma drug resistance." (PMID 32733879, 2020). "Here, the authors show that some recurrent gliomas harbour O-6-methylguanine-DNA methyltransferase (MGMT) genomic rearrangements, and in vitro and in vivo these contribute to temozolomide resistance." (PMID 32753598, 2020). "Most interestingly, we found that 90% of cell cultures showed high expression of MPG with values above 0.4–0.5, whereas mRNA levels of MGMT were significantly different for each glioma primary culture." (PMID 33335215, 2020). "Molecular biomarkers such as isocitrate dehydrogenase 1 (IDH1) and O6-methylguanine-DNA methyltransferase (MGMT) play an important role in evaluating the prognosis of glioma patients." (PMID 33117267, 2020). "The promoter methylation of the MGMT gene in gliomas is a clear example, where it helps to indicate the use of precision medicine through the drug temozolomide." (PMID 33312959, 2020). "For example, O-6-Methylguanine-DNA Methyltransferase (MGMT) methylation is currently used by clinicians for routine evaluation of glioma patients’ therapeutic response to temozolomide." (PMID 32019179, 2020). "Based on a large cohort of 155 patients, we here present the institutional experience for the role of MGMT promotor methylation in glioma WHO grade II." (PMID 33184319, 2020).
glioma (continued). "Substantial evidence gleaned through various retrospective studies on glioma from numerous clinical trials has demonstrated that IDH mutations and MGMT gene promoter methylation have prognostic implications." (PMID 33552543, 2020). "CNS cancer female patients with methylated DNA lived significantly longer as compared to men with the methylated MGMT, showing the importance of sex as a prognostic factor." (PMID 32783304, 2020). "Here, MGMT methylation was found mainly in IDH-mutant gliomas, which is in accordance with the literature." (PMID 31623593, 2019). "For example, promoter methylation of the O6-methylguanine-DNA methyltransferase (MGMT) gene occurs in ~40% of glioma patients and is clinically used as a biomarker of response to alkylating agents." (PMID 31681612, 2019). "We also investigated the relationships between preoperative MGMT autoantibody and treatment response in high‐grade glioma patients who underwent surgery following radiochemotherapy with temozolomide." (PMID 31210005, 2019). "O6-alkylguanine DNA alkyltransferase (MGMT) mRNA in EVs released by reactive astrocyte is taken up by MGMT-negative glioma cells, which induce a temozolomide-resistant phenotype via the translation of MGMT mRNA in EV." (PMID 31447954, 2019). "18F-FDG-PET-based radiomics is a promising method for preoperatively evaluating the MGMT promoter methylation status in glioma and has the potential to guide the treatment and predict the prognosis of glioma patients noninvasively." (PMID 31426864, 2019). "The positive rate of MGMT autoantibody to 20 peptides in glioma groups is compared with healthy individuals, the positive rate of MGMT‐02 (45%), MGMT‐04 (27%), MGMT‐07 (21%), MGMT‐10 (13%), and MGMT‐18 (24%) were significantly elevated in patients with glioma." (PMID 31210005, 2019). "Two other clinical trials have revealed that methylation status of MGMT promoter can predict the prognosis of glioma patients." (PMID 32010632, 2019). "It has been widely used as an MGMT inhibitor and as a sensitizer of glioma cells to alkylating agent TMZ." (PMID 32010632, 2019). "Targeting DNA methylation of specific biomarker gene promoter regions such as MGMT methylation has undoubtedly favored glioma prognosis and improved survival." (PMID 31186453, 2019). "Methylation of the promoter region of the MGMT gene is known to predict the response to alkylating agent's treatment in glioma patients." (PMID 32010632, 2019). "Among the gene markers of gliomas, IDH gene mutations and MGMT methylation are the most critical, and these mutations have an important influence on the prognosis of gliomas." (PMID 31745161, 2019). "According to previous studies, glioma patients with IDH mutation and MGMT methylation generally exhibit a better prognosis." (PMID 31180187, 2019). "The peptides microarrays were incubated with the sera from 378 subjects (67 glioma patients and 311 healthy donors) were used for the serological screening of MGMT autoantibody peptides." (PMID 31210005, 2019). "Regarding MGMT promoter methylation status, we observed that: 100% of 1p/19q codeleted gliomas, 91% of astrocytomas IDH-mutant and 50% of GBM IDH-mutant samples were methylated." (PMID 31623593, 2019). "Undoubtedly, MGMT promoter methylation status is critical for the chemotherapeutic management of glioma, especially for GBM." (PMID 31611911, 2019). "The results showed that TMEM71 was highly enriched in IDH‐wild‐type glioma and MGMT‐unmethylated glioma." (PMID 31180187, 2019). "More interestingly, all patients diagnosed with ITSS grade 0 gliomas showed IDH1 mutations and MGMT promoter methylation." (PMID 31745161, 2019). "Most remarkably, more than 90% of IDH-mutant gliomas exhibit hypermethylation of the MGMT promoter, indicating that these profound epigenetic alterations are strongly associated with IDH mutations." (PMID 31652645, 2019).